KRAS (KRas proto-oncogene, GTPase)
Diseases named in the same sentence as KRAS in open-access papers (continued):
Sharing a sentence is not in itself a finding about the gene and the disease.
metastatic colorectal cancer (continued). "A recent meta-analysis reported that PIK3CA exon 20 mutations are associated with a significantly shorter DFS in KRAS wild-type metastatic colorectal cancer patients treated with anti-EGFR antibody cetuximab." (PMID 25980437, 2015). "The mutation in KRAS exon 2 is a validated biomarker of resistance to anti-epidermal growth factor receptor (EGFR) therapy in metastatic colorectal cancer (mCRC)." (PMID 25886136, 2015). "KRAS mutation assays are important companion diagnostic tests to guide the use of anti-EGFR antibody treatment of metastatic colorectal cancer." (PMID 25568935, 2015). "KRAS mutation assays are important companion diagnostic tests to guide anti-EGFR antibody treatment of metastatic colorectal cancer." (PMID 25568935, 2015). "KRAS is an oncogene, located on chromosome 6, which encodes a protein with an important physiological and pathogenic role in metastatic colorectal cancer (a key protein in EGFR signalling cascade)." (PMID 26557880, 2015). "Mutations in KRAS exon 2 occur in ~35% of all metastatic colorectal cancers (mCRCs), and constitutively activate the mitogen-activated protein kinase (MAPK) pathway." (PMID 25886136, 2015). "CIP2A expression was an independent prognostic marker in patients with wild-type KRAS metastatic colorectal cancer after colorectal liver metastasectomy (relative risk = 1.873, P = 0.019)." (PMID 25896895, 2015). "More than half of the patients selected based on KRAS mutation status fail to respond to the treatment with cetuximab in metastatic colorectal cancer (mCRC)." (PMID 26486455, 2015). "Since 2008 KRAS mutational status has become the main tissue biomarker of resistance to anti-EGFR monoclonal antibodies in metastatic colorectal cancer (CRC)." (PMID 24465771, 2014). "Several studies have found that the KRAS-variant predicts altered response to cetuximab in patients with metastatic colorectal cancer." (PMID 24732316, 2014). "Clinical data regarding the prognostic value of KRAS mutations in patients with metastatic colorectal cancer (mCRC) treated with chemotherapy remain inconclusive." (PMID 25491325, 2014). "Several studies have examined the predictive value of KRAS mutation in codon 61 and/or 146 in metastatic colorectal cancer (CRC) treated with anti-EGFR therapy." (PMID 25361007, 2014). "Recents studies have demonstrated that mutations in the KRAS gene negatively predict the response to EGFR-targeted therapies in patients with metastatic colorectal cancer." (PMID 25267307, 2014). "KRAS activating mutations are widely recognised as predictors of resistance to the treatment with anti-EGFR monoclonal antibodies (moAbs) in metastatic colorectal cancer (mCRC) patients." (PMID 25361007, 2014). "Mutations in KRAS have been associated with metastatic colorectal cancer including peritoneal dissemination with implications for therapy." (PMID 25593974, 2014). "The optimal laboratory assay for detecting KRAS mutations in different biospecimens from patients with metastatic colorectal cancer (mCRC), and the clinical relevance of these gene alterations is still in question." (PMID 25491325, 2014). "Several studies have examined the predictive value of KRAS mutation in codon 61 and/or 146 in metastatic colorectal cancer treated with anti-EGFR therapy (cetuximab or panitumumab)." (PMID 24885062, 2014). "Mutated KRAS was observed in approximately 49.2% (32 patients) of metastatic colorectal cancer in a patient sample comprising 65 individuals." (PMID 29147353, 2013). "KRAS is an EGFR effector in the RAS/RAF/ERK cascade that is mutated in about 40% of metastatic colorectal cancer (mCRC)." (PMID 23548132, 2013). "Recently, first line treatment with cetuximab has been approved in combination with chemotherapy and the benefits of cetuximab was limited to patients with KRAS wild-type tumors, reducing the risk of progression of metastatic colorectal cancer." (PMID 23667824, 2013).
metastatic colorectal cancer (continued). "One such promising molecular diagnostic is Kirsten ras (KRAS) tumor mutation testing for metastatic colorectal cancer (mCRC) patients." (PMID 24403261, 2013). "Mutations in the KRAS gene are associated with poor response to epidermal growth factor receptor inhibitors used in the treatment of metastatic colorectal cancer." (PMID 22534075, 2012). "We evaluated comparability and consistency of KRAS test results among five laboratories currently being used to determine KRAS mutation status of metastatic colorectal cancer specimens in a large, multi-center observational study." (PMID 22534075, 2012). "KRAS mutations negatively affect outcome after treatment with cetuximab in metastatic colorectal cancer (mCRC) patients." (PMID 22569004, 2012). "The association of KRAS gene mutation and response to therapy was first reported in patients with metastatic colorectal cancer, who were treated with anti-epidermal growth factor receptor (EGFR) agents." (PMID 23202889, 2012). "In a recent report, which studied 330 patients with metastatic colorectal cancer, KRAS mutation was also found to be an independent prognostic factor significantly associated with shorter disease free survival but not with overall survival." (PMID 24212832, 2011). "Of metastatic colorectal cancers that are found to be KRas wild type at codons 12/13, 5% to 15% can harbor BRAF mutations and show resistance to anti-EGFR therapy." (PMID 21403829, 2011). "KRAS mutation has been unambiguously identified as a marker of resistance to cetuximab-based treatment in metastatic colorectal cancer (mCRC) patients." (PMID 21686179, 2011). "A recent meta-analysis of 22 studies including persons with metastatic colorectal cancer treated with cetuximab found that progression free and overall survival in persons with wildtype KRAS tumors was better compared to persons with mutated KRAS tumors." (PMID 20877448, 2010). "KRAS mutational analysis is the standard of care prior to initiation of treatments targeting the epidermal growth factor receptor (EGFR) in patients with metastatic colorectal cancer." (PMID 21110880, 2010). "The predictive value of KRAS mutation in metastatic colorectal cancer patients treated with anti-EGFR monoclonal antibodies, cetuximab or panitumumab, has recently been suggested." (PMID 20977739, 2010). "Due to the call for fast KRAS mutation status analysis for treatment of patients with monoclonal antibodies for metastatic colorectal cancer, sensitive, economic, and easily feasible methods are required." (PMID 21197450, 2010). "KRAS mutations occur in 35–45% of metastatic colorectal cancers (mCRC) and preclude responsiveness to EGFR-targeted therapy with cetuximab or panitumumab." (PMID 19806185, 2009). "To further evaluate this finding we analyzed 120 additional patients with unresectable metastatic colorectal cancer who previously had their primary tumors evaluated for KRAS mutational status for clinical purposes." (PMID 20020061, 2009). "The predictive value of KRAS mutation in metastatic colorectal cancer (MCRC) patients treated with cetuximab plus chemotherapy has recently been suggested." (PMID 17375050, 2007). "Therefore, we conducted a prospective, multicenter, epidemiological observational study over one year to determine the geographical distribution of KRAS mutations and their types by gender in metastatic colorectal cancer (mCRC) throughout Turkey." (PMID 40282985, 2025). "Similarly, let-7 downregulation in metastatic colorectal cancer, particularly in the context of KRAS mutations, diminishes therapeutic efficacy of cetuximab." (PMID 41425255, 2025). "derived implications from previous clinical trials and cohort studies that KRAS mutations may have a stronger effect on prognosis in patients with metastatic colorectal cancer, and discussed possible biomarkers to recognize resistance to EGFR inhibition." (PMID 38706597, 2024).
metastatic colorectal cancer (continued). "By extension, it is reasonable to surmise that patients with dMMR/MSI-H metastatic colorectal cancer harboring a KRAS or NRAS mutation may be more likely to recur if immunotherapy is stopped." (PMID 38085001, 2023). "Mutations of the KRAS gene occur in ~40% of metastatic colorectal cancers." (PMID 37190303, 2023). "The frequency of KRAS mutations in metastatic colorectal cancer (mCRC) exhibits global variation." (PMID 37628868, 2023). "More than 40% of metastatic colorectal cancers have KRAS mutations." (PMID 36339570, 2022). "Indeed, it was shown that KRAS mutants promote metabolic dysregulation in cancer cells and that metformin selectively inhibits metastatic colorectal cancer with the KRAS mutation." (PMID 35203528, 2022). "Within the OMITERC prospective study (OMIcs application from solid to liquid biopsy for a personalised ThERapy of Cancer), we explored the prognostic role of liquid biopsy encompassing cell-free DNA (cfDNA) and circulating tumour cells (CTCs) in KRAS mutated metastatic colorectal cancer (mCRC)." (PMID 33953347, 2021). "Approximately 45% of patients with metastatic colorectal cancer harbor KRAS mutations." (PMID 34944853, 2021). "In addition to the established significance in metastatic colorectal cancer, it was also reported that KRAS mutations were correlated with a worse prognosis in stage II/III CRC." (PMID 34221952, 2021). "Given that metastatic colorectal cancer (mCRC) patients underwent genomic profiling for clinically actionable mutations such as KRAS, NRAS, and BRAF analysis routinely with a clinically validated COBAS panel, we rationalized separating this cohort from the remaining patients." (PMID 33014822, 2020). "This is the first study in predictive testing for NSCLC and metastatic colorectal cancer (mCRC) to include this extent of longitudinal scheme data, as well as KRAS proto‐oncogene GTPase (KRAS) and NRAS proto‐oncogene GTPase (NRAS) variants besides EGFR variants." (PMID 31553104, 2020). "The risk of KRAS status may be weakened due to lower incidences of KRAS mutations in NSCLC than in metastatic colorectal cancer." (PMID 29743116, 2018). "In 2009, the US Food and Drug Administration (FDA) approved EGFR-targeted monoclonal antibody therapy with cetuximab and panitumumab in patients with metastatic colorectal cancer (mCRC) along with analysis of KRAS mutation status, which is a predictive biological marker of resistance." (PMID 28797274, 2017). "The aim of the present retrospective study was to analyze clinical outcome and risk factors associated with treatment outcomes according to KRAS status in patient with metastatic colorectal cancer (mCRC) treated with bevacizumab (bev) plus chemotherapy in the first-line setting." (PMID 25888291, 2015). "However, to date, the prognostic value of KRAS mutations in metastatic colorectal cancer remains inconclusive." (PMID 25896895, 2015). "Mutations in codons 12 and 13 of KRAS occur in ~40% of metastatic colorectal cancers." (PMID 25954997, 2015). "Indeed, mutation of KRAS is a predictive marker of cetuximab efficacy in metastatic colorectal cancer patients." (PMID 25896895, 2015). "The aims of the present study were to investigate the detection of KRAS mutations in CTCs from patients with metastatic colorectal cancer (mCRC) and to compare their mutation status during treatment or disease progression with that of the corresponding primary tumors." (PMID 25137394, 2014). "Recently, any activating mutations in the KRAS gene has been proved to be predictor of response to epidermal growth factor receptor-targeted therapies, such as cetuximab and panitumumab, for patients with metastatic colorectal cancer." (PMID 25267307, 2014). "Hence, an alternative method for detecting KRAS gene mutations in these metastatic colorectal cancer patients treated with anti-EGFR is needed." (PMID 24884535, 2014).
metastatic colorectal cancer (continued). "Previous studies showed that the benefits of the anti-EGFR mAb cetuximab among patients with metastatic colorectal cancer are limited to those patients who have colorectal tumor tissues with wild-type KRAS genes, and KRAS genes with mutations are essentially insensitive to EGFR inhibitors." (PMID 24884535, 2014). "KRAS mutations were detected in the CTCs of patients with metastatic colorectal cancer (mCRC)." (PMID 24179521, 2013). "KRAS mutation detection represents a crucial issue in metastatic colorectal cancer (mCRC)." (PMID 24133623, 2013). "Finally, we compared the relationship between KRAS mutation abundance and the efficiency of cetuximab in another 35 metastatic colorectal cancer patients." (PMID 23874486, 2013). "The issue of whether patients diagnosed with metastatic colorectal cancer who harbor KRAS codon 13 mutations could benefit from the addition of anti-epidermal growth factor receptor therapy remains under debate." (PMID 23437064, 2013). "As far as we know, we firstly showed that low abundance of KRAS mutation (<30%) might also benefit from anti-EGFR treatment in metastatic colorectal cancer patients." (PMID 23874486, 2013). "It is now a standard of care to evaluate for KRAS mutation in metastatic colorectal cancer." (PMID 23097702, 2012). "The RAS pathway signature predicts sensitivity to inhibition of MEK and resistance to inhibition of AKT in pre-clinical models, predicts resistance to Cetuximab in metastatic colorectal cancer patients, and appears to be superior to KRAS mutation status for the prediction of RAS dependence." (PMID 20591134, 2010). "A recent phase I trial reported a 44% partial response rate of onvansertib, a PLK1 inhibitor, in the treatment of patients with KRAS-mutated metastatic colorectal cancer, indicating that PLK1 inhibitor might be suitable for the treatment of this specific subtype of cancer." (PMID 40852028, 2025). "The KRAS mutation test is one of the main tests to determine whether the EGFR pathway is functioning properly when anti-EGFR agents are prescribed in patients with metastatic colorectal cancer." (PMID 36083889, 2022). "Furthermore, KRAS mutations are also used as major prognostic biomarkers for therapies that target the EGFR in patients with metastatic colorectal cancer, as cancer bearing KRAS mutations are reportedly unresponsive to anti- EGFR monoclonal antibodies such as cetuximab and panitumumab." (PMID 30504843, 2018). "Therefore, this prospective study addresses the efficacy of cetuximab monotherapy compared to combination with irinotecan in two molecularly defined subpopulations of patients with refractory metastatic colorectal cancer, either “quadruple wild type” tumours or KRAS G13D mutated tumours." (PMID 27246726, 2016). "Considering that KRAS codon 61 and 146 mutations may also confer resistance to EGFR inhibitors, patients who have metastatic colorectal cancer with KRAS mutation in codon 61 or 146 could receive more tailored management through clinical testing of these additional KRAS codons." (PMID 24885062, 2014). "Furthermore, De Roock and colleagues recently reported that chemotherapy-refractory metastatic colorectal cancers harboring a G13D KRAS mutation were more sensitive to treatment with the epidermal growth factor receptor (EGFR) inhibitor cetuximab compared to tumors with other KRAS mutations." (PMID 22382702, 2012). "The high frequency of KRAS mutations in serrated adenocarcinomas also indicates that most serrated adenocarcinomas are natively insensitive to epidermal growth factor receptor-blocking therapies, which are increasingly being used to treat metastatic colorectal cancer." (PMID 21457162, 2011). "For example, KRAS mutations are associated with decreased disease control rate, shorter progression-free survival and reduced overall survival in patients with advanced or metastatic colorectal cancer treated with the EGFR-targeting antibodies cetuximab or panitumumab." (PMID 20591134, 2010).
metastatic colorectal cancer (continued). "KRAS and BRAFV600E mutations are established biomarkers in metastatic colorectal cancer (CRC), but their predictive roles in early-stage disease remain uncertain." (PMID 42162231, 2026). "In this context, we investigated the prognostic and predictive significance of the NOS2/ARG1 axis and immune cell ratios in chemotherapy combined with cetuximab in wt-KRAS metastatic colorectal cancer." (PMID 41573553, 2025). "Inhibition of the epidermal growth factor receptor (EGFR) shows clinical benefit in metastatic colorectal cancer (CRC) patients, but KRAS-mutations are known to confer resistance." (PMID 40329096, 2025). "The prognostic significance of KRAS and BRAF mutations is well-established in metastatic colorectal cancer (CRC) but remains uncertain in early-stage tumors." (PMID 40279317, 2025). "This study aimed to evaluate KRAS and NRAS mutations over an eight-year period to provide a comprehensive understanding of the genetic landscape of metastatic colorectal cancer (mCRC) in Turkish patients." (PMID 40411151, 2025). "Cetuximab, an EGFR-targeting monoclonal antibody, provides beneficial yet limited clinical improvement in KRAS wild-type metastatic colorectal cancer (mCRC)." (PMID 41214390, 2025). "Panitumumab has been shown to confer clinical benefit in patients with metastatic colorectal cancer and wild-type KRAS." (PMID 41340108, 2025). "Circ-EGFR was identified as a novel predictive biomarker for cetuximab efficacy in KRAS wild-type metastatic colorectal cancer, which was successfully translated into a non-invasive liquid biopsy assay for predicting responses to anti-EGFR therapy." (PMID 41214390, 2025). "Background/Objective: The prognostic value of specific hot-spot mutations within KRAS, NRAS, and BRAF genes in metastatic colorectal cancer (mCRC) genes remains debatable." (PMID 40075837, 2025). "The manageable safety profile and promising anti-tumor activity of the combination of onvansertib/FOLIFRI/bevacizumab in the second-line treatment of patients with KRAS-mutant metastatic colorectal cancer (mCRC) was reported." (PMID 40565172, 2025). "For 50% of patients with KRAS/NRAS/BRAF wild-type metastatic colorectal cancer, the median survival after treatment is approximately 30 months." (PMID 38576495, 2024). "The study observed improvements in FCSI and EQ-5D Index scores, particularly favoring the panitumumab + BSC in wild-type KRAS metastatic colorectal cancer, with early dropout rates of 38–42% for panitumumab + BSC and 68% for BSC alone." (PMID 38667537, 2024). "The present study underscores the significance of [18F] FDG PET-CT radiomic parameters, particularly SUVmax, in their association with KRAS, BRAF, and EGFR mutations in metastatic colorectal cancer patients." (PMID 39722096, 2024). "The PRIME study, a randomized phase III clinical trial with 1183 patients, tested panitumumab–FOLFOX4 versus FOLFOX4 alone in untreated wild-type (WT) KRAS metastatic colorectal cancer." (PMID 38790167, 2024). "The aim of this study is to explore the impact of different treatment strategies in a real-world population of patients with metastatic colorectal cancer KRAS wild type and a KRAS mutant." (PMID 39458124, 2024). "This study showed that adagrasib, an inhibitor of the mutant KRAS G12C protein, had antitumor activity in heavily pretreated metastatic colorectal cancer patients, both as a monotherapy and in combination with cetuximab." (PMID 38790167, 2024). "EGFR‐targeted monoclonal antibodies, such as cetuximab, are used to treat KRAS‐wild type metastatic colorectal cancer, but eventually, resistance to this therapy emerges." (PMID 38887984, 2024). "This cohort study identifies the factors associated with likelihood of microsatellite instability and KRAS biomarker testing among patients with metastatic colorectal cancer." (PMID 38967928, 2024).